ADIPOR1 (adiponectin receptor 1)
Diseases named in the same sentence as ADIPOR1 in open-access papers (continued):
Sharing a sentence is not in itself a finding about the gene and the disease.
epithelial ovarian cancer (6 papers, 2016 to 2023). "Decreased expression of adiponectin receptors, mainly AdipoR1, is observed in epithelial ovarian cancer." (PMID 37190027, 2023). "AdipoR1 is an emerging prognostic factor for this malignancy, since many reports evidenced its down-regulation, particularly in the epithelial ovarian cancer cells." (PMID 31052147, 2019). "This study is the first to report a lower expression of AdipoR1 and AdipoR2 in epithelial ovarian cancer cells compared with granulosa tumor cells." (PMID 29603059, 2018). "The expression of adiponectin receptors AdipoR1 and AdipoR2 has been reported in the human ovary and ovarian cancer tissues." (PMID 29603059, 2018). "The basal ADIPOR1 mRNA level was lower in the epithelial ovarian cancer cells (3.5-, 2-, and 1.3-fold in OVCAR-3, SKOV-3, and Caov-3, respectively) than in the granulosa tumor cell line (p < 0.05)." (PMID 29603059, 2018). "There is some research that proves a significant decrease in expression of AdipoR1 and AdipoR2 observed in ovarian cancer cell lines and, more precisely, expression of those receptors was lower in the epithelial ovarian cancer cell line compared with granulosa tumor cell line." (PMID 33809784, 2021). "Indeed, AdipoR1 and AdipoR2 expression is generally lower in epithelial ovarian cancer cells, such as COV434, OVCAR-3 and SKOV-3 cells, compared to granulosa tumor cells, making prognosis worse for this tumor type." (PMID 31052147, 2019). "We aimed to investigate whether adiponectin and its receptors, AdipoR1 and AdipoR2, are expressed in human epithelial ovarian cancer cell lines." (PMID 29603059, 2018). "Additionally, we found that AdipoR1 and AdipoR2 expression is lower in epithelial ovarian cancer cells than in granulosa tumor cells." (PMID 29603059, 2018). "Second, we investigated whether BPA and its analogs could regulate the expression of AdipoR1 and AdipoR2 in epithelial ovarian cancer cells." (PMID 29603059, 2018). "Additionally, our results indicated that both AdipoR1 and AdipoR2 are expressed in various epithelial ovarian cancer cell lines, and that their expression in these cell lines was lower than in the granulosa tumor cell line (COV434)." (PMID 29603059, 2018). "Finally, we investigated whether E2, P4, and IGF-1 can regulate AdipoR1 and AdipoR2 expression and modulate the effects of adiponectin on the proliferation of ovarian cancer cells." (PMID 29603059, 2018). "The authors also showed a correlation between AdipoR1 expression and the FIGO stage and the presence of ascites in patients with epithelial ovarian cancer (EOC)." (PMID 37190027, 2023). "The expression of AdipoR1 and AdipoR2 has been reported in a human granulosa tumour KGN cell line and in various epithelial ovarian cancer cell lines." (PMID 30934676, 2019).
Hepatic steatosis (6 papers, 2012 to 2025). Steatosis is a term used to denote lipid accumulation within hepatocytes. "Moreover, fucoidan has been suggested to upregulate the level of APN and reduce hepatic steatosis in NAFLD through the AdipoR1 cascade." (PMID 38794753, 2024). "Moreover, low adiponectin or AdipoR1 have been shown to predict progression of hepatic steatosis to cirrhosis." (PMID 23092446, 2012).
steatosis (6 papers, 2013 to 2025). Increased lipid within the cytoplasm of cells. "The aim of the present study was to define the potential role of adipocyte-derived adiponectin, and its receptors, adipoR1 and adipoR2, in the pathogenesis of steatosis in patients with CHB." (PMID 23914225, 2013). "Collectively, these observations suggest that THC-ameliorated steatosis might contribute to the upregulation of AdipoR1-AMPK signaling and the AdipoR2-PPARα pathway, thus improving lipid and glucose metabolism in the liver and muscle of HFD/STZ-induced diabetic obese mice." (PMID 34960104, 2021). "The hepatocyte steatosis model was further treated with YCLLT-containing serum and/or silencing AdipoR1." (PMID 39807243, 2025). "AdipoR1 mRNA expression was negatively correlated with HOMA-IR (rs = -0.349, P = 0.043), and grade of steatosis (rs = -0.340, P = 0.049)." (PMID 23914225, 2013). "To confirm the role of AdipoR1/AMPK/SIRT1 signaling pathway in the improvement of HepG2 cell steatosis by YCLLT, we silenced AdipoR1 to further explore the molecular mechanism of YCLLT, and the results showed that silencing of AdipoR1 inhibited the improvement of YCLLT in NAFLD cell model." (PMID 39807243, 2025). "Furthermore, CBD improved alcohol-induced hepatic metabolic dysregulation and steatosis by restoring changes in hepatic expression of ACC-1, FASN, PPARα, MCAD, ADIPOR-1, and mCPT-1." (PMID 35644678, 2022). "Furthermore, CBD improved alcohol-induced hepatic metabolic dysregulation and steatosis by restoring changes in hepatic mRNA or protein expression of ACC-1, FASN, PPARα, MCAD, ADIPOR-1, and mCPT-1." (PMID 28935932, 2017). "The mRNA level of hepatic adipoR1 was similar in NASH, and simple steatosis." (PMID 23914225, 2013). "While mRNA levels of adipoR1, adipoR2, and adiponectin tended to be lower in liver biopsies of subjects with steatosis compared tosubjects without steatosis, suggesting a pathophysiological role for this adipokine in liver diseases." (PMID 23914225, 2013). "The adipoR1 mRNA expression tended to be lower in liver biopsies of subjects with steatosis without reaching statistical significance (4.58 ±0.37 vs. 4.59 ± 0.47, P = 0.880) compared to subjects without steatosis." (PMID 23914225, 2013).
atherosclerosis (5 papers, 2011 to 2022). A disease characterized by the build-up of fatty material and calcium deposition in the arterial wall resulting in partial or complete occlusion of the arterial lumen. "The original aim of this study was to investigate the effect of combined AdipoR1 and AdipoR2 deficiency (AdipoR1-/-AdipoR2-/-) on atherosclerosis." (PMID 24324556, 2013). "In order to study the effects of combined AdipoR1 and AdipoR2 deficiency on atherosclerosis during ApoE deficiency, we first wanted to produce AdipoR1-/-AdipoR2-/- mice." (PMID 24324556, 2013). "AdipoR1 and AdipoR2 mediate metabolic processes and accumulation of lipids in macrophages in atherosclerosis; adiponectin demonstrated the ability to suppress lipid accumulation in macrophages." (PMID 35890325, 2022). "Hence, the adiponectin-AdipoR1/2-APPL1 axis can prevent the formation of macrophage foam cells preventing atherosclerosis." (PMID 35890325, 2022). "We observed that chronic stress aggravated high fat diet-induced atherosclerosis in a mouse model by inhibiting the GLP-1-mediated APN/adipoR1 pathway, and it subsequently enhanced the inflammation and oxidative stress process and changed the properties of atherosclerotic plaques." (PMID 34368136, 2021). "Thus, considering the results from the present study, AdipoR1 and AdipoR2 signalling may have opposing effects in atherosclerosis and it will be important for the future to investigate the effect of AdipoR1 deficiency on the atherosclerosis process." (PMID 24324556, 2013). "Adiponectin may reduce LPS-induced NO production and nitrosative stress and prevent adventitial fibroblasts (AFs) from proliferating, transforming to myoflbroblasts, and migrating to the intima, thus worsening atherosclerosis, by inhibiting the AdipoR1-AMPK-iNOS pathway in AFs." (PMID 21829524, 2011).
breast tumor (5 papers, 2013 to 2025). "Although both are expressed in breast tumour tissue, ADIPOR1 levels are higher than those of ADIPOR2." (PMID 41456223, 2025). "Most previous studies by other groups and our own that analyzed ADIPOQ and/or ADIPOR1 levels were performed on paraffin-embedded breast tumor tissue using immunohistochemistry." (PMID 41456223, 2025). "Multivariable-adjusted associations of body fatness measures with ADIPOR1 protein and ADIPOR1 gene expression in breast tumor tissues." (PMID 35846306, 2022). "Subgroup analysis of the multivariate associations of LEP, LEPR, ADIPOQ, ADIPOR1, and ADIPOR2 IHC expression with breast tumor clinicopathologic features among Black women yielded similar findings." (PMID 32046756, 2020). "A representative figure shows adjacent breast tissue to tumor and breast tumor tissues labeled by indirect immunofluorescence for A) Adiponectin and B) AdipoR1 and AdipoR2 with DAPI as nuclear counterstain." (PMID 26431176, 2015). "Besides, ADIPOR1 protein levels were higher in breast adipose tissue adjacent to tumours in postmenopausal women and in obese women with more aggressive breast tumours." (PMID 41456223, 2025). "In the current study, we hypothesize that measures of body fatness are associated with LEPR, ADIPOR1, and ADIPOR2 expression profiles in the breast tumor microenvironment, which might contribute mechanistically to the development of more aggressive breast tumor phenotypes and poorer prognosis." (PMID 35846306, 2022). "We obtained during surgery fresh breast tumour tissue and a fragment of breast adipose tissue adjacent to the tumour and analyzed the levels of adiponectin (ADIPOQ) and its receptor ADIPOR1 by Western blot." (PMID 41456223, 2025). "Building on our prior research, here we examined the associations of body fatness measures with protein and gene expression of the adipokines, LEP and ADIPOQ, and the adipokine receptors, LEPR, ADIPOR1, and ADIPOR2 in breast tumor tissues." (PMID 35846306, 2022). "Variation in LEPR IHC expression was observed by breast tumor clinicopathologic features, while the expression of LEP, ADIPOQ, ADIPOR1, and ADIPOR2 did not appear to vary by tumor clinicopathology." (PMID 32046756, 2020).
colitis (5 papers, 2018 to 2021). Inflammation of the colon. "Studies looking at the effect of diet-induced obesity on severity of TNBS-colitis and cytokine expression in mouse mesenteric fat suggest that adiponectin receptor 1 aggravates colitis." (PMID 33603741, 2020). "In another DSS-colitis study, induction of colitis significantly decreased adiponectin and increased expression in both AdipoR1 and adiponectin receptor 2 (AdipoR2)." (PMID 33603741, 2020). "Adiponectin expression was significantly suppressed by induction of colitis, and intracolonic silencing of adipoR1 in mice exacerbated TNBS-induced colitis." (PMID 33167521, 2020). "In contrast to the proinflammatory role of leptin, adiponectin maintains intestinal homeostasis and protects against murine colitis through interactions with its receptor AdipoR1 and by modulating adaptive immunity." (PMID 33167521, 2020). "In this study, the long-term overexpression of AdipoR1 exacerbated murine colitis induced by DSS and ADN enhanced the expression of pro-inflammatory factors in macrophage and colon epithelial cells." (PMID 29540173, 2018). "To study the role of AdipoR1-overexpression in DSS-induced murine colitis, we assessed colitis symptoms by body weight loss, bloody-diarrhea, colon-length and histological analysis." (PMID 29540173, 2018). "Previous studies support the protective role of ADN and AdipoR1 in chemically-induced murine colitis." (PMID 29540173, 2018). "To study the physiological role of AdipoR1 in intestinal inflammation, we employed DSS to induce murine colitis in porcine AdipoR1 transgenic mice (pAdipoR1 mice)." (PMID 29540173, 2018). "In this study, we showed a requirement of AdipoR1 signaling in murine colitis through regulating of neutrophil chemotaxis." (PMID 29540173, 2018). "We generated porcine AdipoR1 transgenic mice (pAdipoR1 mice) and induced murine colitis using dextran sulfate sodium (DSS) to study the potential role of AdipoR1 in inflammatory bowel disease." (PMID 29540173, 2018). "Our goal was to clarify the role of AdipoR1 signaling in colitis and the effects on neutrophils." (PMID 29540173, 2018). "However, studies about the role of AdipoRs in colitis are still rare; only the study by Sinderi shows that short-term (2 days) AdipoR1 knock-down exacerbates colitis in mice." (PMID 29540173, 2018). "Silencing of AdipoR1 in mice resulted in an exacerbation of TNBS-induced colitis." (PMID 30369924, 2018). "Therefore, we are the first to use female mice to study AdipoR1 effects in colitis." (PMID 29540173, 2018). "The effects of long-term overexpression of AdipoR1 on colitis are still unknown." (PMID 29540173, 2018). "In vitro, fat-conditioned media lowered AdipoR1 in human colonic epithelial cells (NCM460), while in vivo intracolonic silencing of AdipoR1 in mice exacerbated TNBS-induced colitis." (PMID 33603741, 2020).
coronary artery disease (5 papers, 2011 to 2022). "We aimed to determine adiponectin levels and expression of its receptors (AdipoR1 and AdipoR2) in peripheral monocytes from overweight and obese patients with coronary artery disease (CAD)." (PMID 21284833, 2011). "Likewise, reduced monocyte AdipoR1 and AdipoR2 protein expression was observed in obese adults with coronary artery disease, compared to obese adults without cardiovascular disease." (PMID 29073286, 2017).
diabetic nephropathy (5 papers, 2016 to 2025). "Male AdipoR1-KO mice showed typical signs of early diabetic kidney disease, including albuminuria, glomerular structural abnormalities, and lower expression of central podocyte proteins; females were less affected." (PMID 39874092, 2025).
hepatocellular carcinoma (5 papers, 2018 to 2025). A malignant tumor that arises from hepatocytes. "TXNDC5 modulated adiponectin signalling by interacting with adiponectin receptor 1 (AdipoR1) and contributed to increased risk of hepatocellular carcinoma development." (PMID 29792171, 2018). "Taken together, these findings suggest that AdipoR1 reduces cyclin B1 expression through the E3 ubiquitin ligase CCNB1IP1 in hepatoma cells." (PMID 39849382, 2025). "In our quest to fathom the underlying mechanism, we conducted high-throughput transcriptome sequencing on hepatocellular carcinoma cells in which AdipoR1 had been stably knocked down." (PMID 39849382, 2025). "To explore the mechanism, we performed high-throughput transcriptome sequencing of hepatocellular carcinoma cells with stable knockdown of AdipoR1." (PMID 39849382, 2025). "In particular, isoquercitrin elevated protein expression of adiponectin receptors such as AdipoR1 and AdipoR2 in the rat hepatoma cells." (PMID 32397362, 2020). "In this result, we also found that AdipoR1 knockdown could inhibit the proliferation of hepatocellular carcinoma cells before and after irradiation, and this inhibitory effect was more obvious in the AdipoR1 knockdown combined irradiation group." (PMID 39849382, 2025). "It was reported that isoquercitrin-promoted AMPK activation could enhance AdipoR1 expression and inhibit SREBP-1/FAS expression, resulting in the decrease of lipid accumulation in rat hepatoma H4IIE cells." (PMID 36771140, 2023).
Impaired glucose tolerance (5 papers, 2008 to 2021). An abnormal resistance to glucose, i.e., a reduction in the ability to maintain glucose levels in the blood stream within normal limits following oral or intravenous administration of glucose. "For example, among Caucasian obese individuals (mean BMI 32 kg/m2) with impaired glucose tolerance, ADIPOR1 SNPs were associated with measures of body size including weight, waist, hip circumference and BMI." (PMID 18854016, 2008).
myocardial ischemia (5 papers, 2020 to 2025). A disorder of cardiac function caused by insufficient blood flow to the muscle tissue of the heart. "Interaction between ADIPOR1 and APPL1 diminishes the cardioprotective effects of adiponectin on myocardial ischemia/reperfusion injury in type 2 diabetic mice." (PMID 38049739, 2023).
rheumatoid arthritis (5 papers, 2014 to 2024). A chronic, systemic autoimmune disorder characterized by inflammation in the synovial membranes and articular surfaces. "Our findings establish a novel molecular mechanism by which AdipoR1 regulates the pTh17 pathway to affect rheumatoid arthritis as well as other autoimmune and inflammatory diseases mediated by pTh17." (PMID 39506876, 2024). "This highlights the potential of targeting AdipoR1 to modulate pTh17 cell activity in treatment strategies for rheumatoid arthritis." (PMID 39506876, 2024). "AdipoR1 and AdipoR2 expression was found to be decreased on the surface of B lymphocytes of patients with autoimmune disorders, namely, rheumatoid arthritis and type 1 diabetes." (PMID 31827477, 2019). "Additionally, we examined the expression of adiponectin receptors AdipoR1 and AdipoR2 at the level of mRNA and in the immunohistochemical analysis in synovium samples and infrapatellar fat pad samples from patients with osteoarthritis (OA) and rheumatoid arthritis (RA)." (PMID 35628866, 2022). "High adiponectin and adipoR1 expression levels were found in the synovial fluids and tissues of patients with rheumatoid arthritis, and adiponectin has also been shown to stimulate prostaglandin E2 (PGE2) production in the synovial fibroblasts of individuals with rheumatoid arthritis." (PMID 25525608, 2014).
acute myeloid leukemia (4 papers, 2020 to 2023). Acute myeloid leukemia (AML) is a group of neoplasms arising from precursor cells committed to the myeloid cell-line differentiation. "In human acute myeloid leukemia cells, lncRNA ANRIL inhibits cell senescence by repressing the expression of adiponectin receptor 1 (ADIPOR1), a key regulator of glucose metabolism." (PMID 33109221, 2020). "In acute myeloid leukemia (AML), ANRIL is up-regulated in patients at diagnosis and down-regulated in patients with complete remission; it is proved to modulate the glucose metabolism related pathway of AdipoR1/AMPK/SIRT1 to promote AML cell survival." (PMID 32714094, 2020).
depression (4 papers, 2021 to 2025). "However, the specific roles of AdipoR1 and AdipoR2 in depression-related behaviors and the underlying neural substrates remain to be elucidated." (PMID 31980728, 2021). "The mechanisms by which AdipoR1 in 5-HT neurons regulates depression-related behaviors appear to involve regulation of two key components of 5-HT homeostasis, i.e., synthesis and reuptake." (PMID 31980728, 2021). "In conclusion, our results demonstrate an important role of adiponectin/AdipoR1 signaling in 5-HT neurons in depression-related behaviors and antidepressant responses, which involves in the regulation of key components of 5-HT neurotransmission." (PMID 31980728, 2021). "Selective deletion of adiponectin receptor 1 in the dorsal raphe nucleus specifically could lead to depression-like behavior, and specific knockdown of AdipoR1 with siRNA in the brain is shown to be critical for restoring memory impairment and AD-like neuropathology." (PMID 40426884, 2025).
memory impairment (4 papers, 2016 to 2025). "Overall, our studies demonstrated that osmotin prevented neuroinflammation-associated memory impairment and neurodegeneration and suggest AdipoR1 as a therapeutic target for the treatment of neuroinflammation and neurological disorders, such as AD." (PMID 27093924, 2016). "Furthermore, our study and other interesting and compelling studies reported that neuronal AdipoR1 suppression is associated with metabolic stress, which leads to AD pathology and memory impairment." (PMID 33849621, 2021). "From ADPN-AdipoR1 axis perspective, we hypothesized that loss of AdipoR1 would result in spatial learning and memory impairments as well as neurodegeneration." (PMID 28963462, 2017). "In summary, we found that decreased AdipoR1 expression causes spatial learning and memory impairment and AD-like pathologies, thus suggesting that the ADPN- or ADPN-like ligand-AdipoR1 axis should be considered as a treatment target for AD." (PMID 28963462, 2017). "Because AdipoR1 is upstream of AMPK on the axis, we hypothesized that AKD mice are prone to memory impairment." (PMID 28963462, 2017).
non-alcoholic fatty liver disease (4 papers, 2013 to 2022). "Atractylenolide III activates the hepatic adiponectin receptor 1 (AdipoR1)/AMPK axis to ameliorate non-alcoholic fatty liver disease." (PMID 36558977, 2022).